TUBB3 (tubulin beta 3 class III)
Diseases named in the same sentence as TUBB3 in open-access papers (continued):
Sharing a sentence is not in itself a finding about the gene and the disease.
cancer (81 papers, 2008 to 2025). A tumor composed of atypical neoplastic, often pleomorphic cells that invade other tissues. "TUBB3 acquired mutations have also been associated with different types of cancers such as prostate, pulmonary, renal, gallbladder, and breast." (PMID 40362454, 2025). "TUBB3, which was previously suggested as a cancer cell biomarker, encodes β-tubulin, playing a vital role in various cellular processes, including cell migration and the cell cycle." (PMID 38665698, 2024). "One particular family of miRNAs, the miR-200 family, has been linked to modulating the translation of TUBB3 in the context of cancer." (PMID 35573698, 2022). "Previous studies have reported that upregulation of TUBB3 expression is common and associated with aggressiveness in many cancers, including thyroid cancer." (PMID 35277656, 2022). "Two of these transcription factors have been linked to modulating TUBB3 expression in cancer, SOX4 and SOX9." (PMID 35573698, 2022). "For example, high expression of class-III β-tubulin (TUBB3) has been associated with tumoral tissues and low response rates in patients treated with anti-cancer drugs such as taxanes or vinorelbine." (PMID 36557668, 2022). "This was further supported by studies that found that silencing TUBB3 expression sensitized cancer cell lines to epothilones, a TBA that causes cells to accumulate in G2M phase of the cell cycle." (PMID 35573698, 2022). "TUBB3 protein, encoded by the TUBB3 gene, has the closest relationship with the sensitivity of cancer cells to antimicrotubule chemotherapeutic agents." (PMID 34603450, 2021). "High levels of TUBB3 expression were also described to be associated with poor clinical outcome in various cancers." (PMID 29383151, 2017). "Class III β-tubulin (TUBB3) encodes a neuron-specific protein and is considered to be a marker of cancer severity." (PMID 24926347, 2014). "Among the RBPs that antagonize or facilitate miRNA-mediated repression, a prominent factor is HuR, which affects stability and the translation of numerous genes implicated in cancer aggressiveness, including TUBB3." (PMID 23394580, 2013). "Many preclinical studies have shown that high levels of TUBB3 expression are associated with taxane resistance in various human cancer cell lines, including lung, ovary, prostate, breast, and pancreas." (PMID 24053422, 2013). "TUBB3 is normally only expressed in neuronal cells; however aberrant expression of TUBB3 in several different types of cancers has been shown to cause resistance to paclitaxel." (PMID 20049172, 2010). "Tubulin β 3 (TUBB3) was overexpressed in various cancers and linked to the poor response of MTAs18." (PMID 37752167, 2023). "The presence of Tubb3+ TAMs was highly associated with the cancer-associated nocifensive behaviors such as flinching and licking, suggesting that this previously unknown TAM subset may be capable of promoting tumoral sensation via a direct mechanism." (PMID 36206343, 2022). "However, the occurrence of altered tubulin isotype expressions such as class III β-tubulin (encoded by TUBB3) is prominent in cancers receiving taxane-based therapy." (PMID 27284014, 2016). "To determine the mechanism by which regulated FOXO3a and TUBB3 levels affect P-gp-associated MDR in PTX-resistant cancer cells, we employed transient GFP-tagged-gene and/or siRNA transfections (see the Experimental Procedures) in A549-PacR/5-FU and PC-3-PacR/5-FU cells." (PMID 27284014, 2016). "Potential strategies include tissue-based assessment of intratumoral nerve density using pan-neuronal markers such as PGP9.5 and TUBB3, which correlate with poor prognosis across multiple cancer types." (PMID 41009819, 2025). "TUBB3 encodes class III β-tubulin, a microtubule subunit normally found in neurons but also aberrantly expressed in various cancers." (PMID 41373405, 2025). "TUBB3 response to PI3K/AKT pathway inhibitors was reported to be either upregulated or downregulated in various cancer types." (PMID 39268460, 2024).
cancer (continued). "Here, we validated the decreased mRNA levels of TUBB3 following the treatment of cancer cells with TiNIR and siRNA." (PMID 38665698, 2024). "Coding for a microtubule protein, TUBB3 is overexpressed and related to poor prognoses in various cancers." (PMID 36950012, 2023). "LDHB, PTPRS, UHRF1, and TUBB3 were proposed as universal prognostic and malignancy markers across many cancer types." (PMID 36900348, 2023). "Our results showed that compared with the shNC group, after knocking down TUBB3, the activity of cancer cells was significantly enhanced, while their apoptosis was significantly reduced in the shNC + shTUBB3 group." (PMID 37165308, 2023). "An elevated TUBB3 expression in cocultured GBM signifies its shift in the direction of cancer stemness." (PMID 36834653, 2023). "This review will focus on the normal regulation of TUBB3 transcription, the role of this gene in neurogenesis and development, and on factors contributing to the dysregulation of TUBB3 expression in cancer and drivers of its aberrant expression." (PMID 35573698, 2022). "Further research is required in order to better understand the role that these neuronal factors are playing in TUBB3 expression in cancer." (PMID 35573698, 2022). "Despite the well-established link between βIII-tubulin overexpression, drug resistance and poor clinical outcomes in patients, the regulation of TUBB3 expression in cancer cells remains poorly understood." (PMID 35573698, 2022). "This section will focus on these mechanisms, by discussing what has been learnt about the normal regulation of TUBB3 in healthy tissues, after which the focus will shift to what has been uncovered from studies into dysregulated TUBB3 expression in cancer." (PMID 35573698, 2022). "SOX4 has also been shown to regulate TUBB3 expression cancer, and this will be discussed in a subsequent section." (PMID 35573698, 2022). "The expression of TUBB3 in cancers has also been postulated to play a role in resistance to taxane-based chemotherapy and thus is of great interest to researchers." (PMID 36230740, 2022). "In this study, we found that TGF-β1 was able to trigger the expression of neuronal differentiation marker Tubb3 and neuron development transcription factor Pou4f1 in BMDMs, which was further promoted by the cancer cell–derived secretome in vitro." (PMID 36206343, 2022). "Further studies will be needed in the future to determine the functional significance of TUBB3 nuclear translocation in taxane-resistant cancer cells." (PMID 35631517, 2022). "In cancers where TUBB3 is overexpressed, change in gene expression is often compared to the expression of total β-tubulin." (PMID 35573698, 2022). "Induction of TUBB3 expression has been widely reported in numerous cancer cell lines by both short term and long term exposure to TBAs, a class of chemotherapeutics that target tubulin and microtubule dynamics." (PMID 35573698, 2022). "Despite the relevance of βIII-tubulin protein in development and cancer, there is limited information on the precise elements that regulate the gene expression of TUBB3 in normal and cancerous human cells." (PMID 35573698, 2022). "βIII-Tubulin (TUBB3) is the most commonly found highly expressed β-tubulin isotype that is related to cancer." (PMID 34094924, 2021). "The results of their study confirm that cancer cell sensitivity to paclitaxel treatment is dependent on TUBB3 levels since chemoresistant cells overexpressed this type of tubulin." (PMID 33802861, 2021). "It is worthwhile to mention here that, like TUBB4B, its close relatives TUBB2 and TUBB3 have been shown to predict poor survival, the former regulating the cancer energetics through VDAC and the latter by imparting resistance to microtubule targeting agents." (PMID 35004310, 2021). "TUBB3 is a key mechanism of drug resistance and TUBB3 expression shows predictive value for the prognosis in many cancers." (PMID 32143735, 2020).
cancer (continued). "Docetaxel works as a microtubule stabilizer, and overexpression of βIII-tubulin (TUBB3) was often found in docetaxel resistance in different cancers." (PMID 33014785, 2020). "Several recent reports have shown an interaction between the expression of PTEN and that of TUBB3 in some cancers including PCa." (PMID 31412591, 2019). "TUBB3, the best characterized subunit of the beta-tubulin, is generally upregulated during cancer progression." (PMID 31375012, 2019). "Collectively, these results suggest that TUBB3 is involved in PCa progression and plays an important role in resistance to taxanes across cancer types." (PMID 31412591, 2019). "Given the previous reports that TUBB3 is associated with cancer progression and DTX resistance in PCa, we sought to examine the expression of TUBB3 in a normal prostate cell line (RWPE-1) and PCa cell lines." (PMID 31412591, 2019). "What is more, some studies have reported that overexpression of TUBB3 is involved in DTX resistance in some cancers including PCa." (PMID 31412591, 2019). "Microtubulus-TUBB3 was found overexpressed in several carcinomas suggesting a significant role in cancer development." (PMID 29383151, 2017). "Our data were fully congruent with the results of earlier studies investigating TUBB3 expression in other carcinomas (breast, prostate, renal tumors, stomach, e.g.)." (PMID 29383151, 2017). "The expressions of both TUBB3 and FOXO3a were the highest in cancer cells with derived PTX and GEF resistance." (PMID 27284014, 2016). "In several cancers, class III β-tubulin (encoded by TUBB3) is a predictive biomarker of clinical PTX resistance and a DCT-based chemotherapy response." (PMID 27284014, 2016). "In PacR cancer cells, TUBB3 expression had > 2.8 and > 1.3 fold increases while FOXO3a had > 2.8 and > 1.0 fold increases when compared to both drug-sensitive normal and cancer cells, respectively." (PMID 27284014, 2016). "It is possible that MPTOXmay be used as a complementary medicine alongsideother routine medicines in order to overcomedrug resistance in cancers that express high levelsof TUBB3 and TOPIIA." (PMID 26464822, 2015). "For example, the aberrant regulation of ERCC1, TYMS, TUBB3, RRM1 and TOP2A is associated with the abnormal proliferation of cancer cells, according to the hallmarks of cancer that were proposed previously." (PMID 24926347, 2014). "With regard to chemoresistance, tubulin, beta 3 class III (TUBB3) overexpression has been reported as a primary mechanism of taxane drug resistance in diverse cancers." (PMID 24551595, 2014). "Since NCCIT cells, as reported for many cancer cell lines, express basal level of TUBB3, the relative increase of TUBB3 transcript number due to RA-treatment was only little, but significant." (PMID 23950971, 2013). "Class III β-tubulin (TUBB3) has been shown to play a role in chemotherapy resistance in various cancer types." (PMID 24053422, 2013). "Expression of TUBB3 is known to be a common mechanism of resistance to microtubule-targeting agents in many types of cancer." (PMID 20049172, 2010). "Furthermore, it is known that although TUBB3 is specific for neurons in normal cells, many cancers overexpress TUBB3, which is a factor of poor prognosis and resistance to treatment." (PMID 38744818, 2024). "Thus, further development of taxane-based chemotherapy for hormone-resistant cancer with low TUBB3 expression looks highly promising." (PMID 37065867, 2023). "This review highlights that a combination of transcriptional controls and altered epigenetic modifications, in conjunction with disrupted signalling pathways may all contribute to disrupted TUBB3 expression in cancers and subsequent response to therapy." (PMID 35573698, 2022). "HIF1α and HIF2α may potentially regulate TUBB3 expression in hypoxic conditions by mechanisms that differ in diverse cancer types." (PMID 35573698, 2022).
cancer (continued). "Furthermore, TUBB3/βIII-tubulin expression can be independently induced upon REST siRNA treatment in cancer cells." (PMID 35573698, 2022). "They noted differing patterns of expression of the TUBB3 protein in the various cancers." (PMID 36230740, 2022). "Due to this perturbation of TUBB3 expression in cancer, several studies have investigated whether the altered expression of TUBB3 is a response to chemotherapeutic agents or as a result of gene dysregulation." (PMID 35573698, 2022). "Elucidating molecular mechanisms of TUBB3 regulation in cancer cells could lead to the improvement of existing microtubule-targeted therapies, or also to the development of effective specific TUBB3-targeted therapies." (PMID 35631517, 2022). "Moreover, reduced EZH2 led to significantly reduced binding of LSD1, HDAC1, and DNMT1 to promoter regions of CDH1, CDKN1A, NEUROD1, and TUBB3, in agreement with increased transcription of these genes in cancer cells after EZH2 knockdown." (PMID 31130994, 2019). "Understanding of the well-characterized mechanism of decreased sensitivity of cancer cells to tubulin-binding agents (TBAs) like vinca alkaloids and taxanes, comes from the analysis of TUBB3 and TUBB4B level regulation in non-small cell lung cancer and prostate cancer development." (PMID 31375012, 2019). "However, their expression levels differ and specifically βIII (TUBB3) tubulin is very narrowly distributed in normal cells while it is almost always found in cancer cells and it is often correlated with drug resistance." (PMID 30388878, 2018). "Chronic hypoxia is a major clinical concern in the cancer field, and the potential of HIF-2-directed therapies is now possible, especially given the recent studies that indicate that tubulin beta-3 chain (TUBB3), which is involved in cancer progression and chemotherapy, is a HIF-2 target gene." (PMID 29383635, 2018). "It was shown that overexpression of TUBB3 could be related to reduced efficiency of taxane-based targeting anticancer drugs in several cancer types." (PMID 29383151, 2017). "A gene expression analysis showed that both TUBB3 and FOXO3a mRNA levels are relatively lower in non-cancer RWPE-1 prostate cells, L132 and MRC-5 lung cells, and HEK293 and HUVEC cells whereas their levels are higher in drug-sensitive cancer PC-3 prostate cells and H292 and A549 lung cells." (PMID 27284014, 2016). "The difficulty of identifying TUBB3 effector genes and other interacting factors has been addressed in drug-resistant cancers because of the complexity of tubulin auto-regulation many years before identifying the association of β-tubulin isotypes and PTX resistance." (PMID 27284014, 2016). "Interestingly, most of these genes (25 genes) were down-regulated, and only 3 genes (COL10A1, MMP11, and TUBB3) were up-regulated in cancer tissues." (PMID 26084486, 2015). "There has been great interest in TUBB3 in cancer, as it correlates with resistance to therapy." (PMID 24396456, 2014). "Class III β-tubulin (TUBB3) is emerging as a biomarker in a number of cancers." (PMID 24396456, 2014). "We have shown previously that TUBB3 gene is conditionally expressed as an adaptive mechanism of resistance to low oxygen and glucose levels, conditions correlated with aggressiveness in cancer." (PMID 23394580, 2013). "MM analyzed TUBB3 mRNA and miR-200c expression in cancer samples." (PMID 23394580, 2013). "Understanding the mechanisms that control TUBB3 expression, both in cancer, mature and developing tissues will help to unravel the basic biology of the protein, its role in cancer, and may ultimately lead to the development of new therapeutic approaches to target this protein." (PMID 35573698, 2022). "Moreover, TUBB3 expression has been proven to be associated with aggressive features independent of chemotherapy status in various cancers, including breast, lung, and colon cancer." (PMID 33256003, 2020).
cancer (continued). "TUBB3 knockdown in cancer cell lines that have aberrantly high expression of this gene product were shown to result in increased sensitivity to taxol, whereas ectopic over-expression of this gene in cell lines with low basal expression level of TUBB3 is accompanied by increased resistance to taxol." (PMID 29069726, 2017). "In addition, we found that secretome factors from PTX-resistant cancer cells with acquired cross-resistance support a P-gp-dependent association in multidrug resistance (MDR) development, which assisted the FOXO3a-mediated control of TUBB3 feedback." (PMID 27284014, 2016). "The correlation of point mutations in class III β-tubulin (TUBB3) and the prominent overexpression of ATP-binding cassette P-glycoprotein (ABCB1), a multidrug resistance gene, have been protruding mechanisms of resistance to microtubule disruptors such as paclitaxel (PTX) for many cancers." (PMID 27284014, 2016). "Gene-centric analyses highlight four cancer-relevant loci MAP2K1, FLNC, ABCA1, and TUBB3 as key targets of methylation deregulation, each exhibiting distinct CpG methylation patterns linked to their known biological roles in tumorigenesis." (PMID 41373405, 2025). "The regulatory effects of changes in TUBB3 and TUBB4B levels on cancer progression have been studied." (PMID 35741845, 2022). "The mechanism of action for exosomal miR-200c is tubulin beta 3 Class III (TUBB3) and protein phosphatase 2 scaffold subunit Abeta (PPP2R1B) suppression, which decreases the migration, invasion, and motility of cancer cells." (PMID 36139487, 2022). "They express cancer stem cell markers, such as CD34, MMP2, nestin, and SOX2, as well as the astro-neuronal lineage markers GALC, TUBB3 (CD56), and OLIG2." (PMID 34638987, 2021). "Positivity of protein marker expression for all cancers combined was: ERCC1 20.9%, MGMT 55.4%, RRM1 19.9%, TOPO1 58.7%, TOP2A 75.8%, TS 34.0% and TUBB3 56.8%." (PMID 31479512, 2020). "Changes of TUBB3 and TUBB4B levels have been studied with respect to the regulation of cancer progression." (PMID 31375012, 2019). "As a result, there is expanding interest in evaluating TUBB3 as both a prognostic and predictive biomarker in NSCLC and a number of other cancers." (PMID 24396456, 2014). "Increasing evidence has demonstrated that the expression levels of ERCC1, TYMS, TUBB3, RRM1 and TOP2A are closely correlated with the pathogenesis of carcinomas." (PMID 24926347, 2014). "The mechanisms that lead to TUBB3 expression dysregulation in cancer cells have not been, however, clarified yet." (PMID 39268460, 2024). "The increased expression of CD133, CD9, and CD44, along with SOX9, TUBB3, MGMT, and ABCG2, may have led the GBMs on a path of acquiring cancer-specific stemness." (PMID 36834653, 2023). "By analysing the regulation of TUBB3 and TUBB4B levels in the development of non-small cell lung cancer and prostate cancer, we understand the characteristic mechanism of cancer cells’ reduced sensitivity to vinca alkaloids and taxanes, and other tubulin-binding agents (TBA)." (PMID 35741845, 2022). "Next, we examined the levels of TUBB3 expression in these resistant cell lines and found no altered TUBB3 levels in the four taxol resistant cancer cell lines relative to their respective parental cell lines." (PMID 29069726, 2017). "Tissue microarray statistical results showed that the expressions of BRCA1 and MAPTin cancer tissues were significantly lower (p<0.01) than that in adjacent tissues, whereas the expressions of STMN1 and TUBB3 in cancer tissues were significantly higher (p<0.01) than that in adjacent tissues." (PMID 29113350, 2017). "To elaborate the involvement of TUBB3 in the mechanism by which acquired PTX-resistance and 5-FU cross-resistance develop aggressiveness, we employed various cell-based and protein expression assays that characterize cancer cell invasiveness." (PMID 27284014, 2016).